CD24 (CD24 molecule)
Diseases named in the same sentence as CD24 in open-access papers (continued):
Sharing a sentence is not in itself a finding about the gene and the disease.
pancreatic cancer (continued). "Pancreatic cancer stem cells are commonly defined by expression of CD44, CD24, and ESA on the cell membrane surface." (PMID 24039920, 2013). "Quantitative RT-PCR was performed to measure Bmi1 levels in the CSCs (cell surface markers CD44+CD24+ESA+) and compared to the remaining bulk tumor cells harvested from the human pancreatic cancer xenografts grown in NOD-SCID mice." (PMID 23437065, 2013). "KMC14 cells expressed mRNA of Notch-1, Notch-2, Jagged-1, c-Met, CXCR-4, CD24 and CD44, except Jagged-2, that were reported as pancreatic cancer markers." (PMID 24278411, 2013). "Pancreatic cancer stem cells have been characterized by stem cell markers CD133+ and CD44+/CD24+/EpCAM+ (epithelial adhesion molecule)/ESA (epithelial specific antigen)." (PMID 22570653, 2012). "SHH expression was ~46 times higher in CD44+CD24+ESA+ xenografted pancreatic tumor cells than in normal pancreatic epithelial cells, compared to a 4-fold increase of SHH expression in unsorted pancreatic cancer xenograft cells." (PMID 24213498, 2012). "Decreased IGF-1R expression inhibited the growth of the PANC-1 pancreatic cancer cells and increased the 3-Cl-AHPC-mediated inhibition of CD44+/CD24+sphere size." (PMID 22570653, 2012). "In xenografts derived from primary pancreatic tumors the overlap between ALDHhigh and CD44+CD24+ cells was very limited." (PMID 24213498, 2012). "Using the pancreatic cancer cell line PANC-1, it was also found that CD44+CD24+ cells have a higher in vivo tumorigenic potential than cells expressing either marker, which are in turn more tumorigenic than CD44−CD24− cells." (PMID 24213498, 2012). "The small population of pancreatic cancer cells that expressed ALDH, CD44, and CD24 exhibited the highest tumorigenic potential in vivo, although the differences with cells expressing only ALDH or CD44 and CD24 were not statistically significant." (PMID 24213498, 2012). "Previous reports demonstrated the enrichment of CSCs through the isolation of pancreatic cancer cells co-expressing the cell surface markers CD44 and CD24." (PMID 21695188, 2011). "Firstly, the cell surface markers of pancreatic cancer stem cells, CD44, CD24, and CD133, were evaluated." (PMID 21826251, 2011). "The first report of isolation of pancreatic cancer cells with tumor-initiating properties resulted from selection of cells for CD44, CD24, and ESA (epithelial-specific antigen) cell surface expression." (PMID 21695188, 2011). "Normal pancreatic tissues express very low levels of CD133, CD24, CD44, ESA, Nanog, Notch1, MDR1 and ABCG2 compared to pancreatic cancer and CSCs." (PMID 21304978, 2011). "Moreover, in pancreatic cancer xenografts, ATO in combination with gemcitabine reduced CD24−/CD44+ and ALDH1A1+ CSC populations and inhibited tumor growth." (PMID 38612911, 2024). "It has been reported that cells expressing cell surface markers CD44, CD24 and EPCAM in pancreatic tumors have the potential to promote the formation, proliferation and metastasis of cancer cells, and these cells were entitled as pancreatic cancer stem cell (CSC) by researchers." (PMID 35733218, 2022). "Although its expression in hepatocellular carcinoma cells is not linked with leptin elicited effects, its expression along with other pancreatic cancer stem cell markers (including Oct-4, CD133, CD24/44 and ALDH) is significantly increased in leptin treated pancreatic cancer cells." (PMID 34588926, 2021). "Specifically, the pancreatic cancer stem cell surface marker c-Met reacts to secreted ligands and markers CD44 and CD24 foster intercellular interactions, thereby activating pathways such as Stat3, Notch, and β-catenin in pancreatic cancer stem cells and thus stimulating self-renewal." (PMID 33928036, 2021). "Although the role of CD19+CD24+CD38+ and CD19+CD24+CD27+ regulatory B cells have been investigated in patients with type 1 autoimmune pancreatitis, the specific mechanism of action of CD19 is yet to be determined in pancreatic cancer." (PMID 34737763, 2021).
pancreatic cancer (continued). "Although growth inhibition was achieved by knocking down CD24 in colorectal and pancreatic cancer, no such effects were observed in oral cancer." (PMID 34712602, 2021). "The antitumor ether lipid edelfosine induces apoptosis in CD44+CD24+EpCAM+ pancreatic cancer stem cells (CSCs) and blocks the formation of pancreatic CSC spheroids, derived from the established human pancreatic cancer cell lines as well as from pancreatic cancer patient-derived primary cultures." (PMID 34885233, 2021). "Bitter melon water extract could inhibit CD44+/CD24+/EpCAMhigh CSC populations, decrease CSC markers SOX2, OCT4, NANOG and CD44 and enhance gemcitabine sensitivity in pancreatic cancer models." (PMID 32726914, 2020). "Expression of CD24, CD44, and ESA are enriched in pancreatic cancer stem cells." (PMID 30382189, 2019). "It has been shown that a ninefold increase in Sonic hedgehog mRNA levels were present in the CD44 and CD24 PDAC positive cells compared to the pancreatic cancer cells with low or absent expression of these biomarkers." (PMID 28659655, 2017). "CD24 and CD44 are upregulated in human pancreatic cancer compared to chronic pancreatitis and may be related to the development of pancreatic cancer." (PMID 28659655, 2017). "To understand the biological role of miR-629 in pancreatic cancer progression, miR-629 mimic was transduced into the Capan-2 pancreatic cancer cell line, and we found that miR-629 overexpression significantly increased the population of CD44+CD24+ESA+ cells compared with the control cells." (PMID 29072689, 2017). "CD24 and CD44 are upregulated in human pancreatic cancer compared to chronic pancreatitis." (PMID 28659655, 2017). "Furthermore, in the other pancreatic cancer cell line of HPAC, the expressions of stemness related genes and PAUF were upregulated in CD44+CD24+ESA+ than in CD44-CD24-ESA- HPAC cells." (PMID 29100320, 2017). "Pancreatic cancer sphere cultured from the CFPAC-1 cells showed elevated expression of PAUF and pluripotent stemness genes (Oct4, Nanog, Stat3, and Sox2), and the mRNA of PAUF were increased in CD44+CD24+ESA+ pancreatic CSCs." (PMID 29100320, 2017). "In pancreatic cancer, investigation of cancer stem cell lineages enabled the identification of cell membrane markers such as CD44, CD24, epithelial specific antigen (ESA) and CD133 and the expression pattern of ALDH1A1 as an important biomarker of pancreatic cancer stem cells." (PMID 28671577, 2017). "EMT has also been demonstrated to correlate with CD24+CD44+ and CD133+ cells in pancreatic cancer, providing pancreatic cancer stem cells with a strong migratory capacity, while maintaining their ability to multiply and thus allowing the production of progenies during metastasis." (PMID 26884312, 2016). "Since there is a partial overlap between CD44+/CD24+/ESA+ and CD133+ pancreatic cancer cells, it is conceivable that a combination of the markers may help to mark more pure CSCs than a single marker." (PMID 26458814, 2015). "It has also been observed that the exposure of human MIA-PaCa-2 pancreatic cancer cells expressing high levels of CD44 and CD24 stem cell-like markers to hypoxia and nutrient starvation induced the EMT programme and the expression of HIF-1α and autophagy-related genes." (PMID 23301832, 2013). "There is possibility that inhibition of CD24 might reduce CRC cell proliferation, cell invasion, and metastasis nodules of CRC and pancreatic cancer in mice model." (PMID 23970932, 2013). "CD133+ and CD24+CD44+ESA+ cells are considered pancreatic cancer stem cells, and the proliferation of CD133+ but not CD24+CD44+ESA+ cells was selectively inhibited by low concentrations of metformin." (PMID 23667692, 2013). "In pancreatic cancer, CD44+/CD24+ was demonstrated as potential phenotype to isolate CSCs." (PMID 22693526, 2012).
pancreatic cancer (continued). "In vitro generated gemcitabine resistant pancreatic cancer cells were marked by high expression levels of CD44, while in another study increased CD24 and ESA expression, as well as activation of the c-MET receptor were also detected in gemcitabine resistant cells." (PMID 24213498, 2012). "Notably, the CD44+CD24+ESA+ cells represent a particularly small cell fraction in human pancreatic adenocarcinomas, as this subset comprises less than 1% of the pancreatic cancer cell population." (PMID 24213498, 2012). "Cancer stem cells in pancreatic cancer are defined by the markers CD44, CD24, ESA and CD133." (PMID 22615799, 2012). "We have recently demonstrated that pancreatic CSC's expressing stem cells markers CD133, CD44, CD24, ESA, express high levels of pluripotency maintaining factors, and drug resistance genes MDR1 and ABCG2 as compared to normal pancreatic cells and pancreatic cancer cells." (PMID 23029396, 2012). "Interestingly, there does appear to be some degree of overlap between CD44+CD24+ESA+ and CD133+ pancreatic cancer cells." (PMID 21188169, 2011). "Human pancreatic CSCs expressing high levels of CD133, CD24, CD44, ESA, and aldehyde dehydrogenase also express significantly more Nanog, Oct-4, Notch1, MDR1 and ABCG2 than normal pancreatic tissues and primary pancreatic cancer cells." (PMID 21304978, 2011). "This hypothesis is supported by a report which showed that a highly tumorigenic subpopulation of pancreatic cancer cells express cell surface markers CD44, CD24, and epithelial-specific antigen (ESA)." (PMID 19602232, 2009). "Pancreatic cancer is associated with many CSCs markers that are negative prognostic factors and associated with tumor recurrence and clinical progressions, such as CD133, CD24, CD44, CXCR4, and ESA." (PMID 35892853, 2022). "Regarding the effects of OSM in mediating stemness and pluripotency, OSM was shown to induce a mesenchymal CD44 high/CD24 low phenotype in breast and pancreatic cancer cells, and this action was unique to OSM and not observed following IL-6 exposure in pancreatic cancer cells." (PMID 34361105, 2021). "Indeed, we found that pancreatic cancer stem-like cells expressing CD24/CD44 were targeted by L-fucose liposomes (data not shown)." (PMID 27233074, 2016). "CSC target genes (CD24, EpCAM, BMI1, and LGR5) were also downregulated after JNKi treatment, suggesting that the JNK pathway might play a role in the regulation of CSCs in pancreatic cancer." (PMID 26840266, 2016). "However, CD90+ fibroblast cells were clustered around CD24+ malignant ducts, suggesting that CD90 may be involved in the tumor-stroma interactions and promote pancreatic cancer development." (PMID 25536077, 2014). "Double immunofluorescence staining of CD90 and CD24 showed that the abundant CD90+ fibroblasts were clustered around CD24+ malignant ducts, suggesting that CD90 may be involved in the tumor-stroma interactions and promote pancreatic cancer development." (PMID 25536077, 2014). "The same results were not achieved with CD44-/CD24- pancreatic cancer cells." (PMID 23419168, 2013). "We next examined the expression of stem cell markers (CD133+CD44+CD24+ESA+), pluripotency maintaining factors (Nanog), signaling molecule (Notch-1) and drug resistant genes (MDR1 and ABCG2) in human normal pancreas, primary pancreatic cancer cells, and CSCs by q-RT-PCR." (PMID 21304978, 2011). "Interestingly, the PANC-1 CSC pancreatic cancer spheroids could be subcultured several times for at least seven generations, and these CSC pancreatic cancer spheres, again, contained only 2.8–7.5% of CD44+CD24+EpCAM+ cells after prolonged culture." (PMID 34885233, 2021). "Thus, in pancreatic cancer, the mouse strains used to date do not appear to affect the frequency of tumor initiation, further supporting the idea that CD24/CD44 cells in ALDHhigh and ALDHlow populations are unlikely to contribute to tumor initiation in our studies." (PMID 21695188, 2011).
pancreatic cancer (continued). "As for pancreatic cancer HPC-Y5 cells, although the ratio of CD44+/CD24+ cells did not exhibit a significant change due to the small size of the double-positive cell subset, the subpopulation of CD44−/CD24− cells was increased following fisetin treatment." (PMID 37743465, 2023). "We examined the effect of low concentrations of metformin on different subpopulations of pancreatic cancer cells and found that these selectively inhibited the proliferation of CD133+ but not CD24+CD44+ESA+ cells." (PMID 23667692, 2013). "Considering the small effect of low concentrations of metformin on the proliferation of pancreatic cancer cells in general, it can be inferred that the proliferation of CD133+ cells, but not CD24+, CD44+, ESA+, or CD24+CD44+ESA+ cells, was selectively inhibited." (PMID 23667692, 2013).
breast tumors (97 papers, 2007 to 2026). "CD24 it promotes the initial steps of cell migration, and its expression in breast tumors is associated with metastasis." (PMID 26040280, 2015). "A recent study on 35 breast tumors of the luminal subtype showed that CD44(+) CD24(-/low) tumors were significantly associated with axillary lymph node metastasis compared with those of CD44(+) CD24(+) type." (PMID 24392029, 2013). "Furthermore, higher membranous expression and, in particular, cytoplasmic staining seem to predict malignant transformation, and different patterns of CD24 expression may be associated with different pathological features in breast tumors." (PMID 32544183, 2020). "Incidentally, transcriptional co-activators YAP/TAZ were found to be upregulated in CD44+/CD24-/ALDH+ cells isolated from patient breast tumors and CSC-enriched mammospheres." (PMID 39979255, 2025). "YAP/TAZ was also found to interact with DRP1 in the cytoplasm, with this interaction being exclusive to the CD44+/CD24− cell population isolated from patient breast tumors." (PMID 39979255, 2025). "Nevertheless, there is a growing body of evidence regarding the prognostic value of such molecules as CD24 expressing in the primary breast tumor." (PMID 38806508, 2024). "Our analysis revealed that CD24 was highly expressed in breast tumor tissues and tumor cells, significantly shortening patient survival time." (PMID 39791710, 2024). "The CD44+ genotype in primary breast tumors and metastasis has been positively associated with tumor initiation and progression, metastasis and increased stemness, whereas CD44+/CD24- is considered a hallmark of BC stem cells." (PMID 37298091, 2023). "We showed that the translocation of CD24 from cytosol to cell membrane is a triggering event for the phenotype change of breast tumor cells exposed to drug stress." (PMID 34426608, 2021). "These different considerations highlight the relevance of the use of CD24 as a marker of cell plasticity and transition state in aggressive breast tumor cells." (PMID 34426608, 2021). "Cells with high CD44 and low CD24 expression (CD44+/CD24-) define a CSC-like population in breast tumors 20 that exhibits high tumorigenic potential and drug resistance." (PMID 31762819, 2019). "Verghese et al20 found that let-7 family was downregulated significantly in breast tumor-initiating cells (BT-1Cs) that were enriched with CD24." (PMID 30013305, 2018). "Further characterization of the CD24−/CD44+ BCSC-like subset with other stem cell markers revealed that estrogen-induced breast tumor initiating/cancer stem cells acquire additional phenotypes, such as 49f, EpCam, ALDH1, and CD133." (PMID 30486409, 2018). "Breast tumor stem cells appeared to have low levels of Spinophilin mRNA, and Spinophilin loss correlated with increased stem-like cell appearance in breast tumors, as indicated by an increase in CD44+/CD24- cells." (PMID 29285244, 2017). "Most current studies have demonstrated CD44 and CD24 as proposed markers for isolation of CSC subset in breast tumors." (PMID 29552056, 2017). "Our findings suggest that differences in CD24 expression in advanced luminal breast tumors exist between human patients and the MMTV-PyMT genetic mouse model." (PMID 26978528, 2016). "In the present study, we analyzed the expression of PD-L1 on CD19+ CD24+ CD38+ Bregs in breast tumor patients with and healthy individuals." (PMID 27762298, 2016). "In this study, CD24+CD90+CD45− cells from primary MMTV-PyMT breast tumors were isolated and their clonogenic and tumorigenic abilities were characterized in detail." (PMID 27542270, 2016). "The ESA+CD44+CD24−/low lineage cells isolated from human breast tumors were able to form tumors in eight-week-old NOD/SCID mice." (PMID 25905435, 2015). "The role of CD24+ cells in breast tumors is unclear, whereas studies have shown that CD24− cells are widely described as tumor initiating cells with stem/progenitor-like properties." (PMID 26040280, 2015).